IL4 (interleukin 4)
Diseases named in the same sentence as IL4 in open-access papers (continued):
Sharing a sentence is not in itself a finding about the gene and the disease.
asthma (continued). "The roles of IL-4 and IL-13 in orchestrating the pathogenesis of asthma may help to explain the relationship between high FeNO levels and airflow limitation." (PMID 32824775, 2020). "It has thus been proposed that IL-4 may have an imperative role in the development and persistent of asthma." (PMID 33228581, 2020). "However, significant positive correlations between both IS IL-4 and IL-13 protein level and IS eosinophil count in the asthma group were observed (r = 0.76, p = 0.006 and r = 0.68, p = 0.02, respectively)." (PMID 33203095, 2020). "Reduce airway hyperresponsiveness, airway wall remodeling and goblet cells hyperplasia, suppressed pulmonary eosinophilia and asthma-related cytokines IL-4 and IL-33, altered the microbial community structure and the short chain fatty acids content in the gut of the asthmatic mice." (PMID 32158441, 2020). "This unique immune response is characterized by the production of the allergy-associated T helper cell type 2 (Th2) and Th17 cytokines interleukin 4 (IL-4), IL-13, and IL-17 that drive IgE, eosinophilia, airway hyperresponsiveness and other manifestations of asthma." (PMID 32485866, 2020). "To date, many studies have examined the association between IL4 gene -589 C/T polymorphisms and the risk of asthma, but their outcomes have not been consistent." (PMID 33087044, 2020). "Macrophages are also induced by Th2-activated IL-4, and induced macrophages, in turn, produce nitric oxides and inflammatory mediators such as cycloxygenase-2, induce mucus secretion, and worsen the symptoms of asthma." (PMID 32580518, 2020). "However, dectin-1 signaling was also shown to be associated with CD4+ T cell production of IL-4, IL-13, and IFN-γ to a lesser extent, suggesting an interplay between Th2 and Th17 responses in fungi induced asthma." (PMID 33324573, 2020). "Subsequently, Th2 cells produce cytokines related to asthma, such as IL-5, IL-4 and IL-13." (PMID 32397396, 2020). "Therefore, the asthma profile that shows elevated IL-4, IL-5, and IL-13, characteristic of severe asthma in children, cannot be readily ascribed to adults." (PMID 31336954, 2019). "These genes have been demonstrated to influence a number of key components of asthma pathology, including eosinophil and T cell migration, production of Th2 cytokines (IL-4, IL-5, and IL-13), mast cell degranulation, IgE production, and airway hyperresponsiveness." (PMID 31221987, 2019). "Deletion of IL-4 or IL-13 using monoclonal antibodies has shown a benefit on asthma control." (PMID 30834081, 2019). "The IL-4/IL-13/STAT-6 pathway is a key modulator of asthma pathophysiology." (PMID 31637021, 2019). "Likewise, Pascolizumab, a humanized monoclonal antibody against IL-4 was shown to be ineffective for treating asthma." (PMID 31216735, 2019). "A much lower level of IgG2 is detected in asthma patients than in healthy controls, whereas a higher IgG1 level is detected, perhaps due to Th2-biased cytokine expression in asthma, such as IL-4, which powerfully promotes immunoglobulin class-switching to IgG1." (PMID 31086415, 2019). "Another very recent study, enrolling 1016 infants <12 months in 17 U.S. centers, confirms that high levels of cytokines inducing a Th2 immune response (IL-4, IL-5, IL-13, and Thymic Stromal Linphopoyetin) are significantly related to the onset of asthma in infants up to four years of age." (PMID 31195744, 2019). "In other AAD models, specifically in murine asthma, airway goblet cell hyperplasia was found to be directly induced by Th2-derived IL-9, whereas IL-4, IL-5, and IL-13 independently induce goblet cell hyperplasia, though indirectly via neutrophilic granulocytes." (PMID 30845208, 2019). "Additionally, IL-4-induced autophagy in B cells exacerbated asthma through an mTOR-independent, PtdIns3K-dependent pathway." (PMID 31849968, 2019).
asthma (continued). "· IFN-γ-dependent prevention of experimental asthma in BALB/c offspring · A significant reduction in acetylation levels of histone 4 of the Il4 promoter after OVA challenge · The preventive effect was completely abolished in heterozygous offspring of A. lwoffii F78-treated Tlr2/3/4/7/9−/− dam." (PMID 31507589, 2019). "Th2 cytokines such as IL-4, IL-5, IL-13, and IL-9 also have the same effects on asthma." (PMID 31143692, 2019). "Anti-inflammatory and immunomodulatory effects of O. basilicum extract on asthma were shown by increasing the IFN-γ/IL-4 ratio (Th1/Th2 balance) and decreasing BALF levels of IgE, PLA2 and TP as well as improvement of pathological changes in sensitized rats by the plant." (PMID 31801507, 2019). "Conversely, COPD induced by exposure to biomass smoke might be associated with a predominantly Th2-type lymphocyte production profile, as in asthma, and an increase of IL-4." (PMID 31208466, 2019). "Previous studies have indicated that the Th2 cytokines IL-4 and IL-13 play a part in asthma." (PMID 31151443, 2019). "Importantly, licochalcone A reduced IL-4 production by suppressing Th2 cell activity, improving the pathological features of asthma." (PMID 31226782, 2019). "Moreover, isolated human mast cells produce IL-13 upon IgE-crosslinking, and IL-13 and IL-4 expressing mast cells are found within the airway smooth muscle of asthma patients." (PMID 31191511, 2019). "Additionally, a study of Massoud and colleagues showed that IL-4 and IL-6 are involved in converting induced regulatory T (Treg) cells into TH-17 like cells, therefore potentially contributing to asthma severity." (PMID 31640701, 2019). "Asthma is an eosinophilic/Th2 disorder, and novel therapeutics targeting Th2 cytokines (IL-4, IL-5 and IL-13) and IgE have achieved excellent improvements in disease control, although these therapeutics are applicable to only a sub group of patients in clinical studies." (PMID 31692453, 2019). "TMEM16A expression is controlled by pro-inflammatory stimuli, namely, by the Th 2 cytokines IL-4 and IL-13 and is shown to be induced by asthma-like conditions, that is, in ovalbumin-challenged mice, in pig airway tissues treated with histamine and in biopsies from asthmatic patients." (PMID 31732694, 2019). "Therefore, IFN-γ, IL-4, IL-12 and IgE serve important roles in the pathogenesis of allergy-induced asthma." (PMID 31545493, 2019). "T-cell differentiation to the TH2-subtype, the isotype switch towards IgE and effects on goblet cell hyperplasia and smooth muscle contractility are prevented by blocking IL-4 and IL-13 simultaneously, which may result in improved asthma outcomes." (PMID 31395084, 2019). "In asthma patients, the Th2-related cytokines such as IL-4, IL-5, and IL-13 are usually increased." (PMID 31790411, 2019). "Hence, the possibility of blocking or modulating IL-4 and/or IL-13 aroused great interest among researchers aiming to gain therapeutic benefit in asthma." (PMID 31355170, 2019). "Moreover, IFN-γ/IL-4 ratio significantly increased in a dose-dependent manner compared to the un-treated asthma group." (PMID 31143692, 2019). "Evidences have shown that IL-4 exacerbated asthma via induction of autophagy in B cells." (PMID 30834081, 2019). "This hypothesis is indirectly supported by the efficacy of dupilumab, which inhibits both IL-4 and IL-13 signaling mediated by IL-4Rα, in patients with severe uncontrolled asthma." (PMID 31866859, 2019). "IL-4, IL-5, and IL-13 belong to Th2 cytokines, which play a fundamental effect in asthma." (PMID 30834081, 2019). "Put together, these data suggest that pendrin may be maximally expressed in severe asthma, since, in this pathological condition, IL-17, as well as IL-4 and IL-13, are abundant in the airway epithelia." (PMID 30744098, 2019).
asthma (continued). "Interestingly, although IL‐27 production was increased in the IfitmF–/– mice compared to WT in our asthma experiments, levels of Il4, IL‐5, IL‐13, IL‐6, IL‐10, IL17, and TNF‐α were all decreased." (PMID 30365177, 2019). "Upstream regulator predictions suggested that six inflammatory cytokines were upregulated and one downregulated (Z-Score > 1 or <−1); among the upregulated cytokines, the classical Th2 cytokines interleukin (IL)-4 and IL-5 drive M2 macrophage polarization in asthma pathogenesis." (PMID 31133848, 2019). "IL-4 was high in asthmatic and atopic children as a predictor of asthma condition, whereas IL-5 could predict exacerbations." (PMID 30035104, 2018). "IL-4 and IL-13 are signature type 2 cytokines playing critical roles in the pathogenesis of asthma." (PMID 29642409, 2018). "IL-4, IL-13 and other type 2 cytokines have long been known to be drivers of allergic asthma, and many studies have shown increased chemokine levels in the airways of patients with asthma compared to controls." (PMID 30463560, 2018). "Several genes linked to asthma are regulated by epigenetic mechanism, such as genes involved in T-effector pathways (interferon INF-γ, interleukin-4 (IL-4), IL-13, and IL-17), T-regulatory pathways (forkheadbox P3 [FoxP3]), and airway inflammation (arginase [ARG])." (PMID 29992143, 2018). "Elevation of IL-4, IL-5, IL-9, and IL-13 was noted in asthma cytokine alterations." (PMID 30423980, 2018). "Although allergic asthma has always been considered to be a Th2 disease with increased eosinophils and Th2 cytokines such as IL-4, IL-5 and IL-13, severe asthma related to clinical resistance may result from a mixed Th2/Th17 response." (PMID 29540228, 2018). "Therefore, IgE and IL-4 levels are reportedly higher in OVA-induced asthma model mice than in normal controls." (PMID 30360392, 2018). "IL-4 also increased the bronchial hyperresponsiveness in patients with asthma." (PMID 30210646, 2018). "In experimental asthma models and clinical studies of asthmatic populations, increases in pro-inflammatory cytokines, such as IL-4 and IL-5, are directly related to the differentiation, proliferation, recruitment, and survival of inflammatory cells in allergic inflammation." (PMID 30135462, 2018). "In addition, it would be of interest to investigate other classical targets in asthma disease and to compare the effects of NS preparations on the release of Th2 cytokines IL-4, IL-5, and IL-13 in in vitro models." (PMID 30333747, 2018). "This type of asthma is thought to arise from an imbalance in T helper type I (Th1)-Th2 immune regulation, resulting in increased levels of the Th2 cytokines interleukin (IL)-4, IL-5, and IL-13, which have been proven to be important drivers of allergic airway inflammation in asthma." (PMID 29867963, 2018). "In summary, serum IL-4, IL-5 and IL-10, adhesion molecules, and sE-selectin were all involved in the pathogenesis of allergic rhinitis and asthma, which can be used to diagnose the degree of respiratory allergic diseases, thus being potentially applicable to clinical practice." (PMID 30344593, 2018). "However, the ability of IL-4-, IL-5-, or IL-13-producing Treg cells in the development of asthma needs to be further investigated." (PMID 30013989, 2018). "However, other studies have shown that NLRP3 expression drives the polarization of M2 macrophages in asthma through upregulation of IL-447 and Il4 promoter binding and transactivation in conjunction with the transcription factor IRF448." (PMID 30518854, 2018). "Compared with the control group, the relative expression levels of miR-1 and IFN-γ in the peripheral blood of children with asthma in the study group were significantly decreased, whereas the expression levels of IL-4, IL-5, IL-8, and TNF-α were significantly increased." (PMID 30046607, 2018). "However, they also showed an increased IL-4 production in iNKT cells of asthma patients compared to controls." (PMID 30210497, 2018).
asthma (continued). "Except for IL-4, the other five factors in the combined group were higher than those in the allergic rhinitis group, further proving that allergic rhinitis combined with asthma inflammation is more severe than allergic rhinitis and asthma." (PMID 30344593, 2018). "The US FDA has approved drugs for asthma (anti-IL-5 agents, including mepolizumab, reslizumab, benralizumab, and anti-IgE omalizumab); atopic dermatitis (anti-IL-4/IL-13 agent dupilumab), psoriasis (anti-IL-17 secukinumab and brodalumab), and chronic urticaria (anti-IgE and omalizumab)." (PMID 29707206, 2018). "The classic asthma presentation is generally regarded as a T helper cell type 2 (Th2) airway inflammation, as high levels of eosinophil, total immunoglobulin (Ig) E and Th2 cell-related interleukin (IL)-4, -5, -13 were observed." (PMID 28199353, 2017). "IL-4, IL-5, and IL-13 are essential Th2 cytokines in driving the development of asthma." (PMID 28106744, 2017). "Additionally, olaparib, a kind of PARP inhibitor, protected mice against asthma by suppression of Th2 cytokines such as IL-4." (PMID 29179487, 2017). "Our results may indicate that suppression of either IL‐5 or IL‐4/IL13 is insufficient and it is necessary to suppress both Type‐2 cytokines such as IL‐5 and IL‐4/IL‐13 for the improvement of asthma control." (PMID 28474411, 2017). "In addition, the periodontal treatment (Asthma+P+TP) and the periodontal treatment with PDT in the asthmatic mice with P (Asthma+P+TP+PDT) decreased (p<0.01) the level of IL-4 in the BAL when compared to the (Asthma+P) group." (PMID 29145431, 2017). "Moreover, other researchers demonstrated that in asthma pathogenesis IL-4 can induce similar lung pathology to IL-13, but independent from IL-13 and that IL-13Ralpha1 regulates IL-4-induced responses." (PMID 28533556, 2017). "Furthermore, following gastric bypass surgery and weight loss, there was a significant reduction in these mediators, including in IL-4, the main Th2-cytokine related to asthma." (PMID 28696379, 2017). "Interestingly, the combination of asthma and periodontitis led to a significant reduction in the inflammatory cells (eosinophils, lymphocytes, macrophages) as well as the IL-4 cytokines release in the lungs." (PMID 29145431, 2017). "In a mouse model of house dust mite-induced asthma in which AMs are depleted using clodronate liposomes, Th2 cytokines, such as IL-4, IL-5, and IL-13, and inflammatory cytokines and eosinophil recruitment were increased in BAL fluid, suggesting an immunosuppressive role of AMs." (PMID 28751894, 2017). "The purpose of this study was to explore the associations of interleukin-4 (IL-4), IL-6, and IL-12 levels in peripheral blood (PB) with lung function, cellular immune function, and children's quality of life (QOL) with moderate-to-severe asthma." (PMID 28328807, 2017). "IL-4Rα Q576R, which can affect the binding of IL-4 and phosphorylation of intracellular substrates including signal transducer and activator of transcription 6 (STAT6), has been linked to many autoimmune disorders such as asthma, atopy, and allergy." (PMID 28511637, 2017). "Likewise, the suppression of the clinical activity of asthma by a preparation of a monoclonal antibody against the alpha subunit of IL-4 has been described." (PMID 28696379, 2017). "Initial attempts to block IL-4 alone were unsuccessful for the management of asthma." (PMID 28855973, 2017). "Similarly, mTOR inhibitor treatment during asthma onset restored IL-4, IL-10, and IFN-γ levels to levels similar to those in the control mice." (PMID 28674387, 2017). "Importantly, PT can decrease Th2 cell production of IL-4 to reduce the pathological characteristics of asthma." (PMID 28243240, 2017). "Group 2 innate lymphoid cells (ILC2s) are a relatively newly discovered lymphocyte population that promotes features of allergic airway diseases including asthma and chronic rhinosinusitis through secretion of the type 2 cytokines IL-4, IL-5 and IL-13 among others." (PMID 28959799, 2017).
asthma (continued). "We use human/mouse CD4+ T cells to see whether IL-27 could inhibit IL-4 production in vitro and then observe whether IL-27 administration could alleviate allergic airway inflammation in vivo by mice asthma model." (PMID 27687913, 2016). "In patients with asthma, increased IL-4 protein levels were found in BALF and serum." (PMID 26003185, 2016). "Elevated amounts of IL-4 have also been detected in scleroderma, asthma and tuberculosis." (PMID 26934574, 2016). "In addition to reduced type 2 cytokine protein levels in OVA‐driven asthma, diminished mRNA expression levels of Il‐5, Il‐13, and Il‐4 were observed in CD4‐enriched lung cells from LXRα−/−β−/− mice." (PMID 27621817, 2016). "IL4 rs2243250 was associated with increased FEV240 (Forced Expiratory Flow Volume after 240s of hypertonic saline inhalation; p = 4.81*10−4) and CD14 rs2569190 was associated with asthma diagnosis (p = 1.36*10−3)." (PMID 27624002, 2016). "In addition, the percentage of CD8 cells producing IL-4 spontaneously was higher in children with asthma in this study." (PMID 27799958, 2016). "On the other hand, ELISA results also demonstrated that expression of IL-4, IL-6, and IL-17a was reduced when compared with asthma induced mice and further confirmed that the inflammation response could be inhibited by Nepeta bracteata Benth." (PMID 27073403, 2016). "Biologicals targeting the Th2-eosinophil nexus such as anti–interleukin (IL)-4, anti–IL-5, and anti–IL-13 are ineffective in asthma as a whole but are more effective if patients are selected using cellular (eg, eosinophils) or molecular (eg, periostin) biomarkers." (PMID 26334389, 2016). "Therefore, P2Y6 activated by UDP enhanced mast cell invasion and IL-4 release to modulate mucus hypertrophy in the development of asthma in mice." (PMID 27590515, 2016). "Moreover, alternatively activated macrophages responded to IL-4 and IL-13, key cytokines in asthma pathology and furthermore, promoted a TH2 environment and airway remodeling." (PMID 27007158, 2016). "IgE and IL-4 levels are used as biomarkers for the severity of asthma and allergic diseases." (PMID 26742052, 2016). "A very recent study shows that IL-17A/IL-4 dual producing cells are important in asthma and may provide a potential explanation for ICS use decreasing IL-17A+ cells." (PMID 27552197, 2016). "Recently, asthma endotype cluster analysis followed by genotype or phenotype cluster analysis has achieved successful clinical results, including anti-IL-5 antibody therapy for persistent eosinophilic severe asthma and anti- IL-4 or anti-IL-13 antibody therapy for high-Th2-type severe asthma." (PMID 27965774, 2016). "Several mediators/modulators are involved in asthma pathogenesis and in hyperresponsiveness such as Th2 cytokines (IL-5, IL-4, and IL-13), IL-17, leukotrienes, nitric oxide, Rho kinase, cholinergic system, and others that were clearly evaluated in humans and animal models." (PMID 27445433, 2016). "In the same context, we applied our M(IL-4, IL-13) signature to predict outcomes in asthma cohorts." (PMID 26302899, 2015). "Polymorphisms in IL4 have been associated with increased total serum IgE levels, atopy, and asthma in some populations, but not in others." (PMID 26540410, 2015). "In asthma, there is ample evidence for goblet cell metaplasia involving the conducting airways; IL-4 and IL-13 also induce the production of TGF-β by epithelial cells that, through autocrine signaling, results in the mucus metaplasia that is characteristic of Th2-mediated inflammation." (PMID 26048391, 2015). "Clinical observations of IL-4 in allergic asthma include increased IL-4 in the serum and bronchoalveolar lavage (BAL) of allergic individuals, while nebulized IL-4 given to patients with mild asthma results in a significant increase in AHR associated with the elevation of sputum eosinophil numbers." (PMID 26362930, 2015).